TRIB2 (tribbles pseudokinase 2)
Diseases named in the same sentence as TRIB2 in open-access papers (continued):
Sharing a sentence is not in itself a finding about the gene and the disease.
atherosclerosis (1 paper, 2021). A disease characterized by the build-up of fatty material and calcium deposition in the arterial wall resulting in partial or complete occlusion of the arterial lumen. "Considering that TRIB2 is a highly regulated gene in vulnerable atherosclerotic lesion, and that the inhibition of macrophage IL-10 biosynthesis is a potential pro-inflammatory consequence of high TRIB2 expression, TRIB2 might be associated to both inflammation and atherosclerosis." (PMID 34070799, 2021).
brain tumor (1 paper, 2024). "Regarding TRIB2, we performed a Kaplan–Meier estimator survival analysis with the GlioVis brain tumor cases." (PMID 38794149, 2024).
breast tumors (1 paper, 2024). "Increased expression of myeloid TRIB2 reduces IL-15 levels in breast tumors, resulting in reduced numbers of T cells that are key to the antitumor immune responses." (PMID 39376611, 2024).
colon cancer (1 paper, 2021). "In colonic premalignant polyps, TRIB2 expression was associated with an increased risk for progression to colon cancer." (PMID 34198908, 2021). "The first hint that TRIB2 expression was related to colon cancer was reported in 2013, when TRIB2 protein was detected in CRC samples using tissue microarray analysis (TMA) by IHC." (PMID 34198908, 2021). "Later in 2017, TRIB2 mRNA and protein expression were found to be significantly increased in primary colon cancer tissue samples when compared to matched normal tissue samples." (PMID 34198908, 2021). "While for TRIB1, gene amplification might partially support its increased levels not only in colon, but also in other types of cancer, the mechanism behind TRIB2 overexpression in colon cancer patients is still unclear." (PMID 34198908, 2021). "In SW-48, Colo205 and HT-29 CRC cell lines, though Tribbles levels were not investigated, afatinib treatment (1 or 10 μM, 48 h) also reduced cell viability, representing an opportunity for further studies, in order to establish TRIB2 targeting as a potential strategy for treating colon cancer." (PMID 34198908, 2021). "Using this elegant strategy, it was shown that the mRNA levels of TRIB2 (as well as of DUSP4, dual-specificity MAPK phosphatase were significantly higher in ACVR2A mutant colon cancers compared to wild-type cases." (PMID 34198908, 2021). "However, none of these studies specifically focused on TRIB2 in colon cancer." (PMID 34198908, 2021).
gastric cancer (1 paper, 2023). A primary or metastatic malignant neoplasm involving the stomach. "Specifically focusing on gastric cancer cases (STAD) within the TCGA, we found a very low frequency of TRIBs genetic and genomic alterations (TRIB1: 9.4%, TRIB2: 2.1%, and TRIB3: 2.1%)." (PMID 38254916, 2023).
Graves disease (1 paper, 2021). Graves' disease is an autoimmune disorder that leads to overactivity of the thyroid gland (hyperthyroidism).It is caused by an abnormal immune system response that causes the thyroid gland to produce too much thyroid hormones. "TRIB2 rs1881145 has been associated with Graves' disease in a Chinese study." (PMID 34567510, 2021).
hyperplastic polyp (1 paper, 2021). A polyp found mainly in the stomach and colon. "Along with phosphoinositide-3-kinase regulatory subunit 3 (PIK3R3) and poly(ADP-ribose) polymerase-14 (PARP14) (among others), TRIB2 was up-regulated in sessile serrated polyps (SSA/Ps), while expressed at a lower level in both the right colon and hyperplastic polyps (HPs) samples." (PMID 34198908, 2021). "Despite sharing histological similarities with the typical hyperplastic polyps (HPs), the SSA/Ps lesions are more prone to develop into cancer, which makes this finding clinically relevant and proposes TRIB2 as a useful biomarker to early distinguish colonic lesions." (PMID 34198908, 2021).
lymphoid leukemia (1 paper, 2016). A malignant lymphocytic neoplasm of B-cell or T-cell lineage involving primarily the bone marrow and the peripheral blood. "Our data provide insight into the understanding of the opposing leukemogenic roles of TRIB2 in myeloid and lymphoid leukemia." (PMID 27462446, 2016).
lymphoma (1 paper, 2020). A malignant (clonal) proliferation of B- lymphocytes or T- lymphocytes which involves the lymph nodes, bone marrow and/or extranodal sites. "Hence, we presumed that the decreased protein expression of TRIB2 is caused by TRIB3 knockout-reduced TRIB2 transcription through suppressing the activity of Wnt/β-catenin in lymphoma cells." (PMID 33298911, 2020). "Thus, Trib3 depletion-reduced TRIB2 expression in lymphoma cells may contribute to lymphoma pathogenesis in MycEμCreCD19Trib3F/+ mice." (PMID 33298911, 2020).
macrocytic anemia (1 paper, 2016). Anemia that is characterized by increased red blood cell volume. "Here, we report that knockout of Trib2 in mice induced macrocytic anemia and increased vulnerability to hemolysis." (PMID 27550848, 2016). "Here, we report that Trib2 knockout (KO) mice manifest macrocytic anemia and increase of T lymphocytes." (PMID 27550848, 2016).
Miscarriage (1 paper, 2014). A pregnancy that ends at a stage in which the fetus is incapable of surviving on its own, defined as the spontaneous loss of a fetus before the 22th week of pregnancy. "It comprised four genes (TRIB2, FAM84A, NBAS (NAG) and DDX1), whose molecular functions did not imply an obvious cellular cause for miscarriage." (PMID 25013457, 2014).
multiple sclerosis (1 paper, 2013). A progressive autoimmune disorder affecting the central nervous system resulting in demyelination. "Furthermore, Trib2 has also been characterized as one of the top non-HLA markers associated with susceptibility to multiple sclerosis." (PMID 24090483, 2013).
myelodysplastic syndrome (1 paper, 2023). A clonal hematopoietic disorder characterized by dysplasia and ineffective hematopoiesis in one or more of the hematopoietic cell lines. "Using previous findings in healthy cells as a reference, we analyzed scRNA-seq data obtained from patients with myelodysplastic syndrome (MDS) and detected specific alterations of the expression dynamics of genes involved in erythroid differentiation in all patients with MDS such as TRIB2." (PMID 36629404, 2023).
pancreatitis (1 paper, 2025). Inflammation of the pancreas. "This suggests that AQP3 and TRIB2 may also play a role in regulating the immune microenvironment of pancreatitis." (PMID 40076525, 2025).
prostate adenocarcinoma (1 paper, 2012). "Depletion of PRKAR2B, ADCK2, TRPM7 and TRIB2 significantly decreased HIF-1α accumulation in LNCaP, an androgen-sensitive human prostate adenocarcinoma cell line with low invasive potential." (PMID 22355351, 2012).
prostate tumors (1 paper, 2022). "We found that patient-derived xenografts of prostate tumors overexpress TRIB2 when the mice were treated with enzalutamide at 30 mg/kg/day for 6 weeks." (PMID 34973338, 2022). "Moreover, we found consistent strong expression of TRIB2 in multiple standard NE-type prostate tumor samples." (PMID 34973338, 2022). "We also found a strong positive correlation of TRIB2 in a range of NE-type prostate tumor samples." (PMID 34973338, 2022). "Moreover, we found that a vast majority of the clinically advanced metastatic prostate tumors from enzalutamide-treated patients show a robust increase in the expression of TRIB2 proteins." (PMID 34973338, 2022). "To verify whether the in vitro observation of TRIB2 overexpression is valid in vivo, we comprehensively analyzed prostate tumors in tissue microarrays (TMAs)." (PMID 34973338, 2022). "Furthermore, we found that overexpression of TRIB2 enhances prostate tumor growth in nude mice and these tumors grow uninterrupted with enzalutamide treatment." (PMID 34973338, 2022).
psoriasis (1 paper, 2022). An autoimmune condition characterized by red, well-delineated plaques with silvery scales that are usually on the extensor surfaces and scalp. "Typically, ABCC5 (p = 0.0012), CISD1 (p= 3.9e−10) and TRIB2 (p < 2.22e−16) levels in psoriasis cases increased compared with healthy samples, whereas NR5A2 (p = 1.8e−13), PEBP1 (p < 2.22e−16) and PRKAA2 (p < 2.22e−16) levels decreased in psoriasis samples." (PMID 36685512, 2022). "Typically, CISD1 (p = 3.9e-10), TRIB2 (p < 2.22e−16), and ABCC5 (p=0.0012) levels among psoriasis cases increased compared with healthy controls, whereas PRKAA2 (p < 2.22e−16), ACSF2 (p = 3e−15), TIMM9 (p= 0.049), PEBP1 (p < 2.22e−16) and NR5A2 (p=1.8e−13) levels decreased among psoriasis cases." (PMID 36685512, 2022).
Type 2 diabetes (1 paper, 2017). "Interestingly, the predominant Q84 glutamine variant is unique to the genus Homo, as the rare R variant associated with predisposition to human Type 2 diabetes is found at this position in Trib3 in other vertebrates and in Trib1 and Trib2 in all vertebrates." (PMID 29025897, 2017).
cancer (54 papers, 2011 to 2025). A tumor composed of atypical neoplastic, often pleomorphic cells that invade other tissues. "Dysregulation of TRIB2 has been implicated in promoting tumor growth, metastasis, and therapy resistance, making it a promising target for cancer treatment." (PMID 39520729, 2025). "Trib2 is a pseudokinase associated with cancer and can interact with E3 ubiquitin ligase to control downstream effector protein stability." (PMID 37240251, 2023). "Overexpression of TRIB2 accelerates cancer cell growth, cell cycle progression, and is associated with poor prognosis of CRC patients." (PMID 36505481, 2022). "In human cancer, Trib2 as a cancer-associated pseudokinase and novel oncogene can enhance cell proliferation and stimulate cell cycle arrest." (PMID 33794905, 2021). "Additionally, as a cancer-associated pseudokinase, TRIB2 can interact with E3 ubiquitin ligases and regulate the stability of downstream effectors, which impact various cellular processes such as proliferation, differentiation, migration, and cell death." (PMID 37240251, 2023). "Trib2, recently identified as the cause of cancer drug resistance." (PMID 33794905, 2021). "Moreover, 5k outperformed the TRIB2 binder alone in inhibiting cell proliferation and inducing apoptosis, confirming that TRIB2 protein degradation could be a promising therapeutic strategy for TRIB2-associated cancers." (PMID 39520729, 2025). "Harmine increases sensitivity to anti-cancer medications by reversing TRIB2-mediated alterations in gene expression." (PMID 39954215, 2025). "Overall, TRIB2-targeted degradation with compounds like 5k represents a promising avenue for advancing cancer treatment strategies." (PMID 39520729, 2025). "The multifaceted role of TRIB2 in oncogenesis highlights its potential as a promising therapeutic target for cancer treatment." (PMID 39520729, 2025). "In several human cancers, the effect of Tribbles, including TRIB2, were shown to be mediated by their ability to modulate the PI3K and/or the MAPK pathway (see Section 1)." (PMID 38254916, 2023). "In contrast, only one study reported TRIB2 to be downregulated in MGC-803 GC cells following treatment with the anti-cancer agent dioscin." (PMID 38254916, 2023). "The aerobic glycolysis is then elevated to promote cancer cell proliferation and migration in TRIB2- or PKM2-overexpressed cultures." (PMID 35790734, 2022). "This study reveals the new kinase activity of TRIB2 and its mechanism in cancer metabolism by regulating PKM2." (PMID 35790734, 2022). "Critical role of TRIB2 in cancer and drug resistance to therapy, TRIB2 interacts with MAPKK, AKT and NFkB proteins and participates in cell survival, proliferation and immune responses." (PMID 36300089, 2022). "TRIB2 overexpression obviously promoted cancer cell proliferation and increased tumor weight in vivo compared with those in lv-con treatment." (PMID 35790734, 2022). "The suppression of TRIB2 with shTRIB2 significantly inhibited cancer cell proliferation in vivo compared with that in lv-con treatment." (PMID 35790734, 2022). "In this study, TRIB2 has elevated the p-PKM2 levels in cancer cells and reduced them in TRIB2−/− mutant mice." (PMID 35790734, 2022). "To further explore its role in TRIB2-promoted tumorigenesis in cancer, we used siRNA to knock down RFWD2." (PMID 34646775, 2021). "TRIB2 acts as an oncogene and promotes cancer cell proliferation and migration, whereas RFWD2 knockdown reversed the role of TRIB2 in promoting cancer cell growth and colony formation in vitro and in vivo." (PMID 34646775, 2021). "We have highlighted various studies, which provide evidence of Trib2 protein as an attractive target for cancer therapy." (PMID 33794905, 2021). "In summary, this study reveals that TRIB2 promotes the progression of cancer by affecting the proteasome-mediated degradation of proteins through the interaction with RFWD2." (PMID 34646775, 2021).
cancer (continued). "In order to understand differential expression and activity of TRIB2 in cancer, the network of components acting upstream of TRIB2 have to be dissected and carefully examined in vitro and in vivo." (PMID 34070799, 2021). "In summary, we identified a key regulatory METTL14‐miR‐99a‐5p‐TRIB2 feedback circuit that epigenetically represses p21 through Akt/mTOR/S6K1/HDAC2 to promote cancer stemness and radioresistance in ESCC." (PMID 34586732, 2021). "The highest TRIB2 protein expression from patients with cancer is related with an extremely poor clinical outcomes." (PMID 34646775, 2021). "There is substantial evidence that Trib2 can be a predictive and valuable biomarker for cancer diagnosis and treatment." (PMID 33794905, 2021). "Cell viability was also suppressed following afatinib treatment, indicating that targeting TRIB2 is a potential strategy for treating cancer." (PMID 33414446, 2021). "We further investigated the involvement of HDAC2 in TRIB2‐driven cancer stemness and radioresistance." (PMID 34586732, 2021). "Due to the importance of TRIB2 in disease progression and therapeutic resistance, TRIB2 presents an exciting opportunity for anti-cancer drug development efforts." (PMID 34070799, 2021). "The results of an MTT assay, which was performed to clarify the role of TRIB2 in cancer progression, showed that TRIB2 knockdown inhibited the proliferation of A549 cells, whereas TRIB2 overexpression promoted the proliferation of A549 cells." (PMID 34646775, 2021). "The role of TRIB2 protein in cancer is currently emerging as a result of our growing understanding of its function in physiological processes and due to its diverse interactome." (PMID 34070799, 2021). "The role of TRIB2 in the cancer progression phenotype was further confirmed in these cells, since both proliferation and cell cycle progression were accelerated by TRIB2 overexpression, along with decreased rates of cellular senescence." (PMID 34198908, 2021). "Next, we transiently transfected pcDNA-3.1-TRIB2 or siRNA into A549 cells to determine the role of TRIB2 in cancer after its overexpression or downregualtion." (PMID 34646775, 2021). "TRIB2, as an oncogene, promotes cancer cell proliferation and migration, which can be blocked by knocking down RFWD2." (PMID 34646775, 2021). "We and others showed that TRIB2 confers resistance to several anti-cancer drugs, including PI3K/mTOR inhibitors, gemcitabine, dacarbazine and temozolomide." (PMID 33316942, 2020). "We previously reported TRIB2-mediated resistance to several anti-cancer agents, including the dual PI3K/mTOR inhibitor BEZ235." (PMID 33316942, 2020). "The pseudokinase Tribbles homologue 2 (TRIB2) has been characterized as an important driver of resistance to several anti-cancer drugs, including the dual ATP-competitive PI3K and mTOR inhibitor dactolisib (BEZ235)." (PMID 33316942, 2020). "We show that two naturally occurring alkaloids, harmine and piperlongumine, inverse the gene expression profile produced by TRIB2 and sensitize cancer cells to anti-cancer drugs." (PMID 33316942, 2020). "TRIB2 confers resistance to several anti-cancer drugs, including the PI3K/mTOR inhibitor BEZ235, by inactivating the AKT/FOXO signaling axis." (PMID 33316942, 2020). "Tribbles homologue 2 (TRIB2) has recently been identified as a protein that promotes resistance to several anti-cancer drugs." (PMID 33316942, 2020). "TRIB2 was reported to act downstream of Wnt/TCF, and Wnt/β-catenin activation was shown to induce TRIB2 expression in cancer cells." (PMID 33298911, 2020). "TRIB2 plays a crucial role in regulating various cellular processes in cancer, such as proliferation, apoptosis and drug resistance." (PMID 30541550, 2018). "TRIB2 has been reported to participate in regulating proliferation and drug resistance of various cancer cells." (PMID 30541550, 2018).